CDK16 (cyclin dependent kinase 16)
Diseases named in the same sentence as CDK16 in open-access papers (continued):
Sharing a sentence is not in itself a finding about the gene and the disease.
ovarian carcinoma (2 papers, 2022). A malignant neoplasm originating from the surface ovarian epithelium. "In the combined analysis of CLIP-seq, RIP-seq and RNA-seq data, we identified multiple potential direct binding targets (BCL2L12, RBCK1, E2F4, and CDK16) that may involve in BUD31-mediated ovarian cancer cell survival and proliferation." (PMID 36271053, 2022).
Adrenocortical Carcinoma (1 paper, 2024). "The same trend is generally true for nonsense mutations, with the exception of CDK16 in Adrenocortical Carcinoma (ACC)." (PMID 38951876, 2024).
Alzheimer disease (1 paper, 2024). A progressive, neurodegenerative disease characterized by loss of function and death of nerve cells in several areas of the brain leading to loss of cognitive function such as memory and language. "A handful study also link CDK16 to various type of neuropsychological disorders, such as learning deficiency, altered social behavior in experimental models and Alzheimer diseases." (PMID 38951876, 2024).
autism (1 paper, 2024). Persistent deficits in social interaction and communication and interaction as well as a markedly restricted repertoire of activity and interest as well as repetitive patterns of behavior. "This interaction appears to mediate subsequent interactions with a network of other autism-related genes’ protein, including CYFIP1, MAPT, APBB1, SNAP25, and CDK16." (PMID 39376742, 2024).
Autoimmunity (1 paper, 2024). The occurrence of an immune reaction against the organism's own cells or tissues. "Our findings reveal that CDK16 regulates not only cell cycle-related functions to promote cell proliferation but also the autoimmunity-related functions of the innate and adaptive immune systems, along with other immune-related signaling pathways." (PMID 38261737, 2024).
breast tumors (1 paper, 2022). "CPTAC database analysis revealed that CDK16 protein expression was significantly elevated in breast tumors compared to normal breast tissues." (PMID 35449080, 2022).
lymphoma (1 paper, 2021). A malignant (clonal) proliferation of B- lymphocytes or T- lymphocytes which involves the lymph nodes, bone marrow and/or extranodal sites. "Moreover, 47 cell proliferation-associated genes were found downregulated in Ri-1 cells under hypoxia, including cyclin CCNB1, and cyclin-dependent kinases CDK14, CDK15, and CDK16, which have significant involvement in the lymphoma pathogenesis." (PMID 34440794, 2021).
neuroblastoma (1 paper, 2021). Neuroblastoma (NB) is the most common solid, extracranial childhood tumor. "Using this combined approach, we identified a role for SHP-2 and CDK16 in Cbl/Cbl-b-dependent regulation of extracellular signal-regulated kinase phosphorylation and neurite outgrowth, highlighting their involvement in neuroblastoma cell differentiation." (PMID 33889818, 2021). "To confirm that rebastinib targeted CDK16 in the neuroblastoma cells, we treated SH-SY5Y cells with rebastinib in a concentration based on the determined IC50 value and performed a cellular thermal shift assay." (PMID 33889818, 2021). "Here, we report an association of CDK16 to ERK and Cbl protein-regulated signaling pathways, linking endogenous CDK16 to ERK phosphorylation and neurite outgrowth in neuroblastoma cells." (PMID 33889818, 2021).
pancreatic neoplasm (1 paper, 2019). A benign or malignant neoplasm involving the pancreas. "By partially targeting CDK16, the re-expression of miR-34a in MiaPaC2 cell line with pancreatic neoplasms induces cellular senescence and cell cycle arrest." (PMID 30953512, 2019).
cancer (26 papers, 2013 to 2025). A tumor composed of atypical neoplastic, often pleomorphic cells that invade other tissues. "In the univariate Cox regression analysis (UniCox), CDK16 emerged as a significant risk factor for overall survival (OS) in a range of cancers, namely LIHC, LGG, PCPG, KIRC, UCEC, UVM, BRCA, and MESO." (PMID 38261737, 2024). "This broad association underscores the potential of CDK16 as a marker for monitoring cancer progression across various types." (PMID 38261737, 2024). "Our investigation into the relationship between CDK16 expression and immune cell infiltration revealed that high CDK16 expression is associated with significantly poorer immune cell infiltration in pan-cancer." (PMID 38261737, 2024). "CDK16‐KD and miR‐485‐5p overexpression can both lead to senescence‐associated phenotypes in cancer cells." (PMID 34687270, 2022). "Recent study suggested that increased CDK16 expression was associated with lower overall survival in several types of cancer." (PMID 33135290, 2020). "Although both proteins have been recently implicated in cancer pathogenesis, it is still unclear how the CDK16/CCNY complex exerts its biological activity." (PMID 30992425, 2019). "Whereas both CDK16 and CCNY have been implicated in cell proliferation and cancer, the physiological substrates of the CDK16/CCNY complex have yet to be identified." (PMID 30992425, 2019). "Altered expression and mutation of PRC1 has been linked to human carcinogenesis, while CDK16 is essential for the proliferation of some types of cancer cells." (PMID 30992425, 2019). "The findings contained herein reveal that a number of off‐target effects of dabrafenib, such as NEK9 and CDK16, are inhibited at clinically achievable doses and that this likely contributes to its efficacy, particularly in cancers that lack BRAF mutations." (PMID 29112787, 2018). "In addition to these important biological functions, CDK16 has been implicated in the growth of several cancers and its expression has been found to be significantly elevated in tissues derived from prostate and breast cancers." (PMID 28057719, 2017). "Thus, there is potential benefit to test these compounds in the future in cancers associated with CDK16 overexpression." (PMID 28057719, 2017). "This differential expression pattern of CDK16 highlights its potential as a biomarker for cancer diagnosis and as a therapeutic target, particularly in cancers with significant overexpression." (PMID 38261737, 2024). "Such an environment potentially facilitates the evasion of immune surveillance by tumor cells, thus highlighting the pivotal role of CDK16 in the complex interplay between cancer cells and the immune system." (PMID 38261737, 2024). "In conjunction with our GSEA results, these findings collectively provide robust evidence supporting the expansive pro-cancer effects of CDK16." (PMID 38261737, 2024). "Crucially, CDK16 has been identified as playing a pivotal role in the progression of various cancers, including lung, prostate, breast, melanoma, and hepatocellular carcinomas." (PMID 38261737, 2024). "This underscores CDK16’s importance in cancer progression and its potential influence on immune therapy outcomes." (PMID 38261737, 2024). "In conclusion, the available data support CDK16 as a potential biomarker for cancer diagnosis and prognosis." (PMID 38951876, 2024). "Many studies have suggested a role for CDK16 in driving cancer cell proliferation through diverse mechanisms." (PMID 38951876, 2024). "This study conducts a comprehensive analysis of CDK16’s role in pan-cancer and its function within the TME, thereby highlighting its considerable potential in cancer therapy." (PMID 38261737, 2024). "In our study, we assessed CDK16 expression in a pan-cancer context using data sourced from The Cancer Genome Atlas (TCGA) and the Genotype-Tissue Expression (GTEx) project." (PMID 38261737, 2024).
cancer (continued). "This pattern highlights the importance of monitoring CDK16 levels in these specific cancers for better prognostic assessment." (PMID 38261737, 2024). "Firstly, we observed overexpression of CDK16 in various cancer types, indicating its potential role as a promoter in tumor development." (PMID 38261737, 2024). "Its role in shaping the immunosuppressive tumor microenvironment and influencing the efficacy of immunotherapy highlights the urgent need for developing targeted therapies against CDK16, offering new avenues for cancer treatment and management." (PMID 38261737, 2024). "This correlation is particularly intriguing, as it hints at a more complex role of CDK16 in the genomic landscape of cancer, potentially influencing tumor behavior and response to therapies." (PMID 38261737, 2024). "Further research will help uncover the exact mechanisms of CDK16 and develop new treatment strategies to improve cancer patient outcomes." (PMID 38261737, 2024). "Overall, these data support the possibility that CDK16 contributes to determine the balance between autophagy and apoptosis thereby driving cancer progression, as also proposed by others." (PMID 38951876, 2024). "In conclusion, our research results provide a comprehensive understanding of the role of CDK16 in various cancers and lay the foundation for future research and clinical applications." (PMID 38261737, 2024). "In an effort to delineate the potential roles of CDK16 in the advancement of tumors, a comprehensive Gene Set Enrichment Analysis (GSEA) was carried out, focusing on the expression levels of CDK16 across a spectrum of 33 distinct cancer types." (PMID 38261737, 2024). "Overall, the expanded analysis underscores the significance of CDK16 in a variety of cancers, suggesting its potential utility as a biomarker for prognosis and therapeutic targeting." (PMID 38261737, 2024). "Previous studies have only sparingly assessed the significance of CDK16 in cancer, such as its ability to modulate cancer cell growth and apoptosis through a p27-dependent mechanism." (PMID 38261737, 2024). "In our study, we examined CDK16’s role in various cancers, focusing on its expression, genetic variations, and prognostic relevance." (PMID 38261737, 2024). "Dysregulation of CDK16 has been described in many cancers such as breast, prostate, cervical cancers, and melanomas." (PMID 36499165, 2022). "In summary, CDK16 mRNA levels and APA‐caused 3′UTR length changes had opposite trends in cancer and cellular aging processes." (PMID 34687270, 2022). "APA‐mediated 3′UTR length changes showed opposite trends between cancer (shortening) and senescence (lengthening), accompanying the up‐ and down‐regulation of CDK16 gene expression, respectively." (PMID 34687270, 2022). "In conclusion, our study provides new insights into the roles of atypical CDKs in cancer and emphasizes that CDK16 is a promising therapeutic target for TNBC." (PMID 35449080, 2022). "CDK16 knockdown results in advanced G2 mitotic arrest and abnormal centrosome dynamics in cancer cells, indicating that CDK16 plays a crucial role in cancer cell proliferation." (PMID 36299580, 2022). "Our finding that PRC1 is a substrate of CDK16 is of particular interest, considering the roles of these two proteins in cancer cell proliferation." (PMID 30992425, 2019). "As CDK16 is emerging as a critical node in cancer, our study reveals novel potential therapeutic targets." (PMID 30992425, 2019). "PRC1 downregulation decreased cell viability in all tested cancer cell lines except for HeLa cells, whereas CDK16 downregulation decreased cell viability in all cell lines." (PMID 30992425, 2019).
cancer (continued). "In cancer cells, CDK16 is involved in cell cycle regulation through its interaction with p27KIP1, where it catalyzes p27 phosphorylation at S10, resulting in its degradation." (PMID 29112787, 2018). "Taken together, these data identify CDK16 as a potential target for the development of novel anti-cancer drugs." (PMID 28057719, 2017). "The most potent CDK16 inhibitors revealed by cell-free and cell-based assays were the multitargeted cancer drugs dabrafenib and rebastinib." (PMID 28057719, 2017). "Our findings revealed that CDK16 was notably overexpressed in 23 out of 33 cancer types examined." (PMID 38261737, 2024). "Furthermore, we delved into the relationship between CDK16 and immune therapy, which holds significant importance in the current landscape of cancer immunotherapy." (PMID 38261737, 2024). "Recognizing the potential importance of CDK16 in cancer, we conducted a comprehensive analysis of CDK16 in a pan-cancer context, investigating its expression, genetic alterations, biological functions, and its relationship with immune regulation and treatment response." (PMID 38261737, 2024). "Furthermore, when combined with our GSEA results, it becomes evident that CDK16 exerts a broad pro-oncogenic effect across multiple cancer types." (PMID 38261737, 2024). "Therefore, we investigated the correlation between ICIs and CDK16 expression across multiple cancer types." (PMID 38261737, 2024). "Additionally, CDK16 regulates the extrinsic apoptosis pathway in prostate and breast cancer cell lines, contributing to cancer cell resistance to TNF-family cytokines, through the stabilization of RIPK1." (PMID 38951876, 2024). "Additionally, CDK16 as a potential target for immunotherapy warrants further investigation to expand the application of immunotherapy in cancer treatment." (PMID 38261737, 2024). "On the other hand, it is speculated that the expressed difference of CDK16 in different cancer cells might affect the selectivity of F8 and F8·2HCl against cancer cells." (PMID 37497111, 2023). "Moreover, knockdown of CDK16 in different cancer cell lines like SCC has been shown to lead to late G2/M phase arrest followed by apoptosis, an effect that was mediated through regulation of the tumor suppressor p27." (PMID 36499165, 2022). "Collectively, these data support that CDK16 inhibition is involved in multiple cancer-related signaling pathways, which may contribute to the function of CDK16 in regulating TNBC progression together with PRC1." (PMID 35449080, 2022). "Therefore, CDK16, whose downregulation results in cancer cell senescence can serve as a potential novel target for cancer treatment." (PMID 34687270, 2022). "Although previous studies have reported that CDK16 is highly expressed in tumors and promotes cancer cell growth, whether it has a function in inducing cancer cell senescence remains unknown." (PMID 34687270, 2022). "Therefore, APA‐mediated 3′UTR length changes explain, at least in part, the opposite gene expression of CDK16 in cancer and senescence models." (PMID 34687270, 2022). "Interestingly, the CDK16 3′ UTR was shortened in cancer and lengthened in senescence models, which was regulated by alternative polyadenylation (APA)." (PMID 34687270, 2022). "Therefore, CDK16 inhibition can induce senescence in both cancer and normal cells, suggesting a universal role of CDK16 in cellular senescence." (PMID 34687270, 2022). "In addition, the results showed that CDK16 was involved in regulating the pluripotency of stem cells, suggesting the potential regulatory role of CDK16 in cancer stem cells (CSCs)." (PMID 35449080, 2022). "The present study found that CDK16‐KD can induce cancer cells to senescence." (PMID 34687270, 2022). "Next, we investigated whether the effect of CDK16 on different types of cancer cell lines was also mediated via PRC1 phosphorylation." (PMID 30992425, 2019). "This implies that the p27 regulation by Cdk16 is a common machinery in human cancers." (PMID 29629337, 2018).
cancer (continued). "To evaluate the clinical importance of Cdk16, we also studied primary tumor samples In primary tumors from the patients with breast, prostate, cutaneous basal, or SCCs, Cdk16 was expressed more highly in cancer lesions than in normal tissues." (PMID 29629337, 2018). "Moreover, we showed that gene knockdown of Cdk16 sensitizes cancer cells to TNF-family cytokines, such as Fas-ligand and TNF-related apoptosis-inducing ligand." (PMID 29629337, 2018). "TUNEL staining showed increased apoptosis of cancer cells treated with Cdk16 siRNA." (PMID 29629337, 2018). "Furthermore, CDK14, CDK16, CDK18 and cyclin Y have all been linked to cancer cell proliferation, migration or cancer drug resistance." (PMID 28057719, 2017). "This suggests that CDK16 could play a significant role in the disease course of these cancers." (PMID 38261737, 2024). "Therefore, CDK16‐KD‐induced downregulation of membranous PD‐L1 may prevent cancer cells from evading immune recognition and thus benefit patient survival." (PMID 34687270, 2022). "In summary, we have identified dabrafenib as a potent inhibitor of NEK9 and CDK16, and our studies suggest that inhibition of these kinases may have activity against cancers that do not harbor BRAF mutations." (PMID 29112787, 2018). "Our studies identified NEK9 and CDK16 as two dabrafenib‐specific kinase targets and provide evidence that inhibition of NEK9 and CDK16 may underlie the greater effectiveness of this drug against NRAS‐ and KRAS‐mutant cancer cells." (PMID 29112787, 2018). "Using data from diverse databases for 33 cancer types, we applied methods like GSEA to assess CDK16’s impact on tumor progression and its connection to immune pathways." (PMID 38261737, 2024). "Analysing the top 100 co‐expressed genes of UBA1 in pan‐cancer on GEPIA2.0, the top 5 genes (CDK16, ELK1, KDM5C, RBM10 and TBC1D25) were highly correlated with UBA1 in most cancer types." (PMID 39183260, 2024). "In summary, CDK16, whose expression is regulated by APA in both cancer and senescence, is a potential novel therapeutic target for senescence‐mediated tumor suppression." (PMID 34687270, 2022). "CDK16 knockdown also leads to a reduced expression of MYC and membrane programmed cell death‐ligand 1 (PD‐L1), two possible factors contributing to cancer cell senescence and immunotherapy effects, respectively." (PMID 34687270, 2022). "The present study found that CDK16 is a CDK undergoing APA, with 3′UTR shortening in four cancer types and lengthening in four cellular senescence models." (PMID 34687270, 2022). "Consistently, in the present study, CDK16‐KD led to decreased MYC expression and senescence of cancer cells." (PMID 34687270, 2022). "Of note, USP9X (log2FC/FDR = −0.31/1.7e-06), a previously reported cancer driver, TXLNG (−0.54/3.3e-17), OFD1, MED14, and CDK16 are known to evade X-inactivation and were over-expressed in females’ GC." (PMID 32849808, 2020). "High CDK16 expression was predictive of a shorter DFI in PRAD, LIHC, SARC, and ACC, indicating its potential as an early marker for recurrence or progression in these cancers." (PMID 38261737, 2024). "Of note, CDK16 knockdown led to a reduced expression of MYC proto‐oncogene, bHLH transcription factor (MYC) and CD274 molecule (PD‐L1), which in turn enhanced the tumor‐suppressive effects of senescent cancer cells." (PMID 34687270, 2022). "It is likely that NEK9 and CDK16 inhibition may contribute to the activity of dabrafenib, perhaps suggesting utility of this drug in other, non‐BRAF‐mutant cancers." (PMID 29112787, 2018). "In these cases, the effects of CDK16 silencing in the RAS‐mutant cancer cell lines were recapitulated through dabrafenib, but not vemurafenib, treatment." (PMID 29112787, 2018). "CDK16 (also known as PCTAIRE1 or PCTK1) is an atypical member of the cyclin-dependent kinase (CDK) family that has emerged as a key regulator of neurite outgrowth, vesicle trafficking and cancer cell proliferation." (PMID 28057719, 2017).